LAG3 (lymphocyte activating 3)
Diseases named in the same sentence as LAG3 in open-access papers (continued):
Sharing a sentence is not in itself a finding about the gene and the disease.
cancer (continued). "Notably, checkpoint pathways with a known role in the APC/Th interplay, such as TIM-3, LAG-3, and TIGIT, are among the most promising checkpoint targets in the cancer immunotherapy pipeline." (PMID 36389687, 2022). "Several inhibitory immunoreceptors, including but not limited to PD-1, CTLA-4, T cell immunoglobulin, and mucin domain containing-3 (TIM3), lymphocyte-activation gene 3 (LAG3), and T cell immunoreceptor with immunoglobulin and ITIM domain (TIGIT), have been identified and characterized in cancer." (PMID 36291797, 2022). "Common immune checkpoint targets that have been reported for having a promising effect, including Lymphocyte activation gene-3 (LAG-3), T cell immunoglobulin and ITIM domain (TIGIT), and indoleamine 2,3-dioxygenase, have presented significance with B4GALNT1 in several cancers." (PMID 35935585, 2022). "It is notable that most immuno-suppressive genes were negatively related to m7G scores through 33 cancers, such as famous drug targets PD1 (gene: PDCD1, ≥30 cancers), CTLA4 (gene: CTLA4, ≥27 cancers) and the next immune checkpoint receptor LAG3 (gene: LAG3, ≥27 cancers)." (PMID 36092891, 2022). "In addition, AP3S1 was positively correlated with most immunosuppressive genes, including PD-1, PD-L1, CTLA4, LAG3 and TIGIT in most cancer types." (PMID 35874816, 2022). "In addition, we found that macrophage subpopulations (clusters 1, 5, 7, 8, and 9) from cancer tissues expressed a certain number of immunosuppressive genes, such as VEGFA, MMP14, MMP19, S100A2, APOE, HMOX1, SLAMF7, SIRPα, LAG3 and IL18." (PMID 36158683, 2022). "Moreover, correlation between KIF15 and immune gene set was analyzed, and the expression of several important immune-related genes was significantly related to KIF15 expression level in pan-cancer, such as CTLA4, IDO1, and LAG3." (PMID 35359374, 2022). "Previous studies have shown that anti‐PD1 could enhance the cytotoxic effect of T cells by upregulating the T‐BET transcription, which lays the foundation of co‐targeting LAG3 and PD1 in cancer immunotherapy." (PMID 35894707, 2022). "All these findings together suggested that ADH1B, LAG3, and HAVCR2 were significantly down-regulated in cancer tissues, which would offer a good prospect that targeted ADH1B could increase the therapeutic efficacy of OV patients." (PMID 35756990, 2022). "Immunotherapy for GEC includes targeted blockade against immune checkpoints such as PD-1/PD-L1, cytotoxic T lymphocyte antigen-4 (CTLA-4), T cell immunoglobulin-3 (Tim-3), lymphocyte activation gene-3 (Lag-3) and chimeric antigen receptor T-cell (CAR-T) cell therapy; and therapeutic cancer vaccines." (PMID 36505480, 2022). "Cancer prognosis is importantly determined by immunosurveillance efficacy, which is critically influenced by the expression of immune checkpoint-related genes, such as PD-L1, CTLA-4, and LAG-3, in cancer cells." (PMID 35963646, 2022). "As previously reported, in the cancer-immunity cycle, CD28: (CD80, CD86), CD40, CD27, HVEM, GITR: GITRL, ICOS, and TLR-2 are stimulatory factors, while TIM-3, PD-L1: PD-1, PD-L1: (CD80, CD86), CTLA-4: (CD80, CD86), BTLA, and LAG-3 are inhibitory factors." (PMID 35419462, 2022). "In addition to PD-1/PD-L1 and CTLA-4 as the most important immune checkpoints, emerging evidence indicates LAG3, TIM-3, TIGIT, VISTA, and other immune checkpoints are the representative ones in malignant tumor." (PMID 35991556, 2022). "CCNA2 was positively correlated with expressions of CD274, CTLA4, HAVCR2, LAG3, PDCD1, and TIGIT in most cancer types, which indicated the CCNA2 expression may act as a marker after immunotherapy." (PMID 35480884, 2022). "Besides, our research manifested the correlation of SLC7A11 with 8 IC genes, namely CD274 (also known as PD-L1), HAVCR2, LAG3, SIGLEC15, PDCD1LG2, CTLA4, PDCD1, and TIGIT in 33 cancer types." (PMID 36267158, 2022).
cancer (continued). "Furthermore, TOP2A was positively associated with expression of immune checkpoints (CD274, CTLA4, HAVCR2, LAG3, PDCD1 and TIGIT) in most cancer types." (PMID 35778520, 2022). "Furthermore, CCNA2 is positively associated with expressions of immune checkpoints (CD274, CTLA4, HAVCR2, LAG3, PDCD1, and TIGIT) in most cancer types." (PMID 35480884, 2022). "Induced CAR-T cells could express immune checkpoint molecules such as PD1 and lymphocyte activation gene 3 (LAG3) or CD223, thus deterring CAR-T anticancer function upon interaction with corresponding ligands expressed by cancer cells." (PMID 35508982, 2022). "In addition, we studied the relationship between the expression of KCC2 (SLC12A5) and NKCC1 (SLC12A2) in pan-cancer and immune checkpoint genes, including SIGLEC15, IDO1, CD274, HAVCR2, PDCD1, CTLA4, LAG3, and PDCD1LG2." (PMID 35372048, 2022). "CTLA4, PDCD1, and LAG3 were significantly up-regulated in 4–5 cancers, while all of them were not dysregulated in PRAD." (PMID 35741849, 2022). "With respect to ‘immunocloaking’ the inhibitory receptors, Fc receptor-like protein 6 (FCRL6) and lymphocyte activation 3 (LAG3) are captured by MHC II on CD4+, CD8+ T cells and NK cells, thus achieving inhibition of immunity against cancer cells expressing MHC II." (PMID 36430404, 2022). "FGL1 was recently identified as a major functional ligand of the immune inhibitory receptor, lymphocyte-activation gene 3 (LAG3), thus making it a promising target for cancer immunotherapy except for the classical programmed cell death protein 1/programmed cell death ligand 1 (PD-1/PD-L1) axis." (PMID 34975333, 2022). "Although the blockade of LAG3 does not result in the same effects as the PD-1 blockade, several studies have already focused on utilizing LAG3 as a target in cancer therapy." (PMID 36051357, 2022). "The binding of LAG-3 to a type of antigen-presenting complex called MHC II keeps the T cells in the inactive state, inhibiting them from being able to kill other cells, including cancer cells." (PMID 36009853, 2022). "At present, cancer immunotherapies include immune checkpoint inhibitor therapy, adoptive cell immunotherapy(ACT), cancer vaccine and some emerging immunotherapy (including LAG3、TIM3、VISTA and B7-H3)." (PMID 36505487, 2022). "PD1 and LAG3 have been reported as the most prevalent T-cell immune checkpoint receptors in RCC, and their blockade to increase IFNγ signaling was considered crucial for successful anti-cancer immunosurveillance." (PMID 34215851, 2021). "CRC is a cancer with high expression of LAG-3, so targeting LAG-3 may be an excellent therapeutic approach to treat such solid tumors." (PMID 34572263, 2021). "Furthermore, evidence for cancer therapy by inhibition of alternative checkpoints such as T cell and mucin-domain containing-3 (TIM-3), lymphocyte activation gene-3 (LAG-3) and T cell immunoreceptor with immunoglobulin and ITIM domain (TIGIT) is emerging." (PMID 34733287, 2021). "LAG-3 plays a regulatory role in immunity and emerged some time ago as an inhibitory immune checkpoint molecule comparable to PD-1 and CTLA-4 and a potential target for enhancing anti-cancer immune responses." (PMID 34067904, 2021). "More important, LAG3 may synergize with CTLA4, PD1/PDL1, and other immune checkpoints, thereby contributing more evidence to improve combination cancer immunotherapy by simultaneously targeting LAG3, PD1/PDL1, and CTLA4." (PMID 34267742, 2021). "Furthermore, we analyzed the correlation between PSME genes and the expression of immune checkpoint-relevant genes, including PD-L1, PD-1, LAG3, and CTLA4, in 33 cancer types in TCGA database." (PMID 34650966, 2021).
cancer (continued). "In addition, LAG-3 co-expression with other immune checkpoint molecules such as CD274 and IDO1 in TILs serve as a prognostic biomarker for cancer prognosis." (PMID 34067904, 2021). "Immune exhaustion marker genes (such as PD-L1, CTLA-4, LAG-3 and HAVCR2) have been demonstrated to play significant role in immune suppression in multiple tumors and several target inhibitors have also been widely applied to immunotherapy for cancers." (PMID 34844602, 2021). "More detailed studies on the putative role of LAG-3 in γδ T cells in the context of cancer are lacking." (PMID 34572874, 2021). "A comprehensive study across more than 1,100 samples of the Cancer Cell Line Encyclopedia showed that nearly 90% of T cell coinhibitory/costimulatory genes, among them LAG3, were not expressed or had low expression across the included cancer cell lines." (PMID 32861198, 2020). "PD‐L1 and LAG3 can be induced by IFN‐γ, the same as IDO1, and this may partially explain their positive correlation in cancer samples." (PMID 32227579, 2020). "Follow-up studies, performed using additional cancer cell lines, namely MC38 and CT26, indicated that a partial initial response to PI3Kδ inhibition is an essential prerequisite to a sequential therapeutic benefit of anti-LAG3 antibodies." (PMID 33093155, 2020). "With all carcinoma types pooled, neither the expression of LAG3 nor of CD8 on TILs had a significant prognostic impact." (PMID 32232506, 2020). "The other molecules involved in immune-inhibitory pathways, such as lymphocyte activation gene-3 (LAG-3, CD223), T cell immunoglobulin-3 (TIM-3), and B7 homolog 3 (B7-H3, CD276), which are considered potential targets of cancer immunotherapy, can also be targeted by antibodies." (PMID 30658461, 2019). "Also, PD-1 blockade combined with other checkpoint blockades, such as Tim-3, LAG-3, or TIGIT, significantly reverses T cell dysfunction and enhances antitumor immunity in patients with cancer, compared to individual checkpoint blockade." (PMID 31379886, 2019). "Then, like other ICs, LAG3 is elevated during HIV, cancer, tuberculosis, and hepatitis B and C." (PMID 30653605, 2019). "This discrepancy may be due to the differential regulatory role of sLAG3 in mediating interaction between LAG3 and MHC-II, or the distinct immune landscapes of different cancer sites." (PMID 31783776, 2019). "The development of a Nb targeting human LAG-3 could enable LAG-3 imaging in cancer patients, which could be used for patient stratification and predicting therapeutic outcome of LAG-3 targeting cancer treatments." (PMID 31569553, 2019). "The third phase (escape phase) begins when cancer cells become capable of binding and activating the co-inhibitory molecules on the T lymphocytes (CTLA-4, PD-1, LAG-3, TIM-3), and secreting soluble immunosuppressive or inducing the secretion of mediators such as IDO, TGFβ, IL10." (PMID 29492219, 2018). "Pegilodecakin treatment induced the hallmarks of CD8+ T-cell immunity in cancer patients, including the systemic elevation of IFNg and GranzymeB levels, expansion and activation of CD8+ TILs, invigoration and expansion of PD-1+/Lag-3+ CD8+ T-cell sub-set and the de-novo expansion of T-cell clones." (PMID 30400835, 2018). "In addition, we noticed that the correlation between PD-1 and other immune checkpoints including LAG3, CTLA-4 and TIGIT is different for different types of cancer." (PMID 30607140, 2018). "Interestingly, multiple genes encoding cell surface immune checkpoint receptors and their ligands were transcriptionally regulated by IRF4, including PD-L1 (CD274), PD1 (CD279), CTLA4 (CD152), B7-2 (CD86), LAG3 (CD223), and PD-L2 (CD273), in these virus-infected cancer cells." (PMID 40733503, 2025).
cancer (continued). "Importantly, CAIX expression was also associated with PD-L1 expression and other immune-inhibitory signatures (FOXP3, TGF-β, LAG-3, TIM-3), supporting the notion that metabolic stress directly contributes to immune dysfunction in the TME, allowing for cancer progression." (PMID 41226466, 2025). "LAG-3 may serve as a depletion marker similar to PD-1 in CD8+ T cells, particularly in response to repeated antigen stimulation during chronic viral infections or cancer." (PMID 40356928, 2025). "Notably, TNFRSF18, LAG3, and PVR exhibit significant differences in 13 to 15 cancers." (PMID 40867324, 2025). "We corroborated in cSCC patient samples that the frequency of GzmB+ cells decreased and the frequencies of CD8+PD-1+, CD8+LAG-3+, CD8+TIM-3+ and CD8+TIGIT+ cells increased in mixed and mesenchymal patient cSCCs, which are those tumors enriched in hybrid E/M and mesenchymal cancer cells." (PMID 38914547, 2024). "In accordance with our hypothesis, a negative correlation was observed between LAG3 expression and the efficacy of cancer cell eradication (step 7), which confirmed its role as an inhibitory immune checkpoint that suppresses immune surveillance." (PMID 38277212, 2024). "Therefore, LAG3 serves as the third clinical checkpoint in case of limited or even no response in 60 to 80% of cancer patients in PD1/CTLA-4 axis immunotherapy." (PMID 38291496, 2024). "Furthermore, unlike CD4 LAG‐3 restrains T cell responses and antibodies targeting this receptor are emerging drugs in cancer immunotherapy." (PMID 39560030, 2024). "The duality of prognostic significance of LAG-3 suggests that focusing on LAG-3 expression alone may not be sufficient to predict the clinical outcome of cancer patients." (PMID 39660130, 2024). "Increased numbers of LAG3 + cells within GC tissue could be a sign of crosstalk between cancer and immune cells rather than a sign of exhausted, dysfunctional T cells." (PMID 37311986, 2023). "Our findings revealed a positive correlation between the expression levels of LAG3 and IFNG (R = 0.76, p < 0.001), PRF1 (R = 0.75, p < 0.001), FASLG (R = 0.75, p < 0.001), GZMH (R = 0.74, p < 0.001), NKG7 (R = 0.74, p < 0.001), and PDCD1 (R = 0.73, P < 0 0.001) in pan-cancer tissues." (PMID 38115039, 2023). "Only clinical testing of anti-LAG-3 in other cancer types and not in OAC yet." (PMID 37520544, 2023). "Monoclonal antibodies targeting inhibitory immune checkpoints, including CTLA-4, PD-1, Programmed Cell Death 1 Ligand 1 (PD-L1), and Lymphocyte-Activation Gene 3 (LAG-3) capable of interfering with negative signals provided by these molecules have revolutionized cancer treatment." (PMID 37296876, 2023). "Moreover, immune checkpoint genes (such as PD1/PD-L1, LAG-3, CTLA-4, and HAVCR2) have been certified to participate in the immune suppression process of multiple tumors and targeted inhibitors have also been applied to specific immunotherapy for cancers." (PMID 35754848, 2022). "We further explored the correlation between the expression of LIPT1 and eight immune checkpoints (PD-L1, CTLA4, HAVCR2, LAG3, PDCD1, PDCD1LG2, SIGLEC15, and TIGIT), and found that LIPT1 levels were correlated with the expressions of these immune checkpoints, especially PD-L1, in most cancer types." (PMID 35837286, 2022). "The lymphocyte activation gene-3 (LAG3), the pathway of the T-cell immunoglobulin and the ITIM domain, the T-cell immunoglobulin mucin-3 (TIM-3), and the V tomorrow-containing IG suppressor of T-cell activation (VISTA) are some examples of the alternative immune checkpoint that cancer cells use." (PMID 36499710, 2022). "We performed an additional in silico analysis of TIM3, LAG3, TIGIT, B7-H6 and CD47-SIRPa to explore the correlation of these markers of immunomodulation in situ by using the online platform TIMER, which is based on 10,897 samples across 32 cancer types from The Cancer Genome Atlas (TCGA)." (PMID 33805268, 2021).
cancer (continued). "In addition, as the immune checkpoints are often used to escape immune surveillance by cancer cells, we also explore the response of checkpoint inhibitors (e.g., PD-1, PD-L1, PD-L2, CTLA-4, LAG3, and TIM-3) and discovered that many of these genes significantly increased in the high-risk group." (PMID 34712325, 2021). "The frequent co-expression of LAG-3 with other immune checkpoint inhibitors such as PD1, PD-L1, CTLA-4, and TIM-3 strongly indicates that LAG-3 might contribute to immune escape mechanisms in cancer." (PMID 34199722, 2021). "Besides evidence that the exhausted phenotype of MAIT cells following exposure to bacterial antigens can be reversed by LAG-3 blockade, the role of LAG-3 in these cells in the context of cancer or inflammation is unknown." (PMID 34572874, 2021). "Although PD-1, CTLA-4, LAG-3, and TIM-3 are equally important in CD8+ T cells, this may highlight the synergistic effect of Ogr1 and existing immunosuppressive checkpoint inhibitors in the treatment of advanced cancers." (PMID 34158625, 2021). "This assay is much simpler than existing methods for determining the activity status of the FGL1-LAG-3 pathway and for designing and detecting new LAG-3/FGL1-related cancer immunotherapies based on patients’ circling FGL1, which might be convenient for use in clinical trials." (PMID 33633363, 2021). "Anti-LAG3 antibodies and CXCR4-targeted therapies are currently being investigated in clinical trials (NCT03470922, NCT02907099, NCT04177810), and our study provides additional rationale to develop these therapeutic strategies, particularly for cancers that arise from or metastasize to the liver." (PMID 33985562, 2021). "When we used the colon-derived cancer cell line MC-38, we observed a poor response to PI3Kδ-blockade, which could not be improved by the addition of LAG3-specific antibodies, suggesting other immunosuppressive mechanisms dominate in these tumors." (PMID 33093155, 2020). "Furthermore, a soluble recombinant LAG-3–Ig fusion protein, i.e., IMP321, has been studied as an immunological adjuvant for vaccination against cancer, and it was able to promote cytokine production of NK cells in a healthy individual and cancer patients in ex vivo culture conditions." (PMID 32640575, 2020). "To evaluate the efficacy of MIR155HG in predicting cancer patient response to checkpoint inhibitor, we used the TIMER database to analyze the relevance of MIR155HG and the currently available blocking molecules with superior therapeutic effects PD‐1, PD‐L1, CTLA4, LAG3, TIM3." (PMID 31568700, 2019). "Therefore, multi-targeting of LAG-3, TIM-3, PD-1, and/or CTLA-4 may serve as a next generation cancer immunotherapy." (PMID 31292525, 2019). "Extensive preclinical murine cancer models and clinical development efforts have been undertaken for a number of co-inhibitory, or immune checkpoint, receptors that have been characterized as identifying exhausted T cells, including CTLA-4, PD-1, LAG-3, TIM-3, and TIGIT." (PMID 30858925, 2019). "Interestingly, disease-associated TEX in chronic infection were further characterized by co-expression of inhibitory receptors TIGIT and 2B4 (as well as some KLRG1 and CD160) while in cancer, TEX more frequently exhibited higher expression of CTLA-4, Lag-3, and CD39." (PMID 32038613, 2019). "Therefore, we need to use modern advanced biotechnology to optimize the molecular structure of LAG-3 inhibitors, clarify the functional and molecular mechanism characteristics of LAG-3 in more detail, and design more reasonable LAG-3 targeted therapy for various malignant tumors." (PMID 39252941, 2024). "In addition, newly discovered immune checkpoints (ICs) such as lymphocyte-activation gene 3 (LAG3), T cell immunoglobulin and mucin domain 3 (Tim-3), as well as T cell immunoreceptor with immunoglobulin and ITIM domain (TIGIT) are also attracting attention in the field of cancer immunotherapy." (PMID 38817600, 2024).